PPIP5K2 (diphosphoinositol pentakisphosphate kinase 2)
Description:
Bifunctional inositol kinase that acts in concert with the IP6K kinases IP6K1, IP6K2 and IP6K3 to synthesize the diphosphate group-containing inositol pyrophosphates diphosphoinositol pentakisphosphate, PP-InsP5, and bis-diphosphoinositol tetrakisphosphate, (PP)2-InsP4. PP-InsP5 and (PP)2-InsP4, also respectively called InsP7 and InsP8, regulate a variety of cellular processes, including apoptosis, vesicle trafficking, cytoskeletal dynamics, exocytosis, insulin signaling and neutrophil activation. Phosphorylates inositol hexakisphosphate (InsP6) at position 1 to produce PP-InsP5 which is in turn phosphorylated by IP6Ks to produce (PP)2-InsP4. Alternatively, phosphorylates PP-InsP5 at position 1, produced by IP6Ks from InsP6, to produce (PP)2-InsP4. Required for normal hearing.
Synonyms: HISPPD1; KIAA0433; VIP2; CFAP160; DFNB100; IP7K2
Tractability: Small molecule: a structure with a bound ligand is known. PROTAC: ubiquitination databases record sites on it; its protein half-life has been measured; a small molecule that binds it is known.
Target class: Enzyme; Transferase
Gene: Protein-coding gene on chromosome 5 (103,120,149 to 103,212,799, forward strand). Ensembl gene ENSG00000145725.
Subcellular location: Cytoplasm, cytosol
Subcellular location (Human Protein Atlas): Vesicles
Pathways (Reactome):
Metabolism: Synthesis of pyrophosphates in the cytosol
Gene Ontology:
Molecular function: 5-diphosphoinositol pentakisphosphate 1-kinase activity; ATP binding; inositol hexakisphosphate 1-kinase activity; inositol hexakisphosphate kinase activity; protein binding; diphosphoinositol pentakisphosphate kinase activity; inositol hexakisphosphate 5-kinase activity; inositol-1,3,4,5,6-pentakisphosphate kinase activity
Biological process: inositol metabolic process; inositol phosphate metabolic process
Cellular component: cytosol
Genetic constraint (gnomAD): Loss-of-function variants: 71 observed, 88.89 expected, observed/expected ratio (o/e) 0.8, 90% interval 0.66 to 0.97. The upper end of that interval is the gene's LOEUF score, 0.97, which puts it in group 4 of 6, group 1 being the genes least tolerant of losing a copy. Missense variants: 711 observed, 1,079.7 expected, observed/expected ratio (o/e) 0.66, 90% interval 0.62 to 0.7. Synonymous variants: 352 observed, 364.23 expected, observed/expected ratio (o/e) 0.97, 90% interval 0.88 to 1.06.
Gene-disease validity (ClinGen):
ClinGen rates the evidence that PPIP5K2 causes each of these diseases.
hearing loss, autosomal recessive (autosomal recessive): Limited. Autosomal recessive form of nonsyndromic deafness.
Homologues: Orthologues: chimpanzee PPIP5K2 (99% identical), macaque PPIP5K2 (99% identical), dog PPIP5K2 (98% identical), pig PPIP5K2 (98% identical), rabbit PPIP5K2 (97% identical), mouse Ppip5k2 (95% identical), guinea pig PPIP5K2 (95% identical), rat Ppip5k2 (94% identical), tropical clawed frog ppip5k2 (84% identical), zebrafish ppip5k2 (77% identical), Drosophila melanogaster l(1)G0196 (58% identical), Caenorhabditis elegans F46F11.1 (46% identical). Paralogues in human: PPIP5K1 (67% identical).
Diseases named in the same sentence as PPIP5K2 in open-access papers:
PPIP5K2 is named in the same sentence as 24 diseases in open-access papers, as found by Europe PMC text mining. Sharing a sentence is not in itself a finding about the gene and the disease. The quoted sentences say what the papers report.
keratoconus (5 papers, 2019 to 2025). A degenerative, structural disorder of the eye, characterized by a cone-shaped protrusion of the cornea. "Naturally occurring human variants of PPIP5K2 have been associated with hearing loss and familial keratoconus." (PMID 38339341, 2024). "The fact that the variant cosegregates in the affected subjects (paternal inheritance) and that variants in the PPIP5K2 gene have been described in keratoconus leads us to propose it as a candidate gene." (PMID 37895187, 2023). "Recent whole-genome sequencing in familial keratoconus patients identified mutations in PPIP5K2 that were responsible for 1-IP7/IP8 synthesis." (PMID 32397291, 2020). "This is the first study to suggest the role of PPIP5K2 coding variants in the genetic etiology of keratoconus." (PMID 31852976, 2019). "Variants in the Diphosphoinositol pentakisphosphate kinase 2 (PPIP5K2) gene may contribute to familial keratoconus (KC) pathogenesis, although the underlying molecular mechanisms remain elusive." (PMID 41533938, 2025). "A gene-trap mouse model harboring a small deletion of the PPIP5K2 phosphatase domain leads to irregularities on the surface of the cornea and pathological corneal thinning, which are similar to keratoconus." (PMID 32397291, 2020).
colorectal cancer (4 papers, 2017 to 2025). A primary or metastatic malignant neoplasm that affects the colon or rectum. "As for the function of PPIP5K2 in cancers, it has been reported that the PPIP5K2 was highly expressed in colorectal cancer (CRC) and associated with a poor prognosis of CRC patients 27-30." (PMID 35813475, 2022). "For instance, a model of seven-gene signatures (NHLRC3, ZDHHC21, PRR14L, CCBL1, PTPRB, PNPO and PPIP5K2) was applied to predict OS by dividing colorectal cancer (CRC) patients into low-risk and high-risk groups." (PMID 28827775, 2017). "PPIP5K2 is highly expressed in colorectal cancer (CRC) and enhances the proliferation and migration abilities of CRC cells." (PMID 40230795, 2025). "It has been observed that PPIP5K2 possesses an important function in the tumorigenesis of a number of cancers, including ovarian and colorectal cancer, suggesting that PPIP5K2 is a potentially significant oncogene in malignancies." (PMID 38339341, 2024). "Through facilitating DNA homologous recombination repair, PPIP5K2 has been proven to be essential for improving colorectal cancer survival in our previous research." (PMID 38339341, 2024). "In addition, PPIP5K2 has been reported to have a significant impact on the maintenance of hematopoietic stem cell activity and tumorigenesis of colorectal cancer." (PMID 38339341, 2024). "Although PPIP5K2 is known to be associated with the survival risk of colorectal cancer 27, 59, 60; to our knowledge, its function has not been reported yet in ovarian cancer." (PMID 35813475, 2022). "In our previous study, we confirmed that PPIP5K2 could be dephosphorylated, entered the nucleus after DNA damage, and participated in DNA homologous recombination repair to regulate the tumorigenesis of colorectal cancer." (PMID 38339341, 2024).
deafness (3 papers, 2018 to 2023). An inherited or acquired condition characterized by the complete loss of the ability to hear from one or both ears. "Our in vitro biochemical studies indicate that the p.Arg837His deafness-associated variant of PPIP5K2 has reduced phosphatase activity and increased kinase activity." (PMID 29590114, 2018). "In conclusion, the identification of the PPIP5K2 variant as a risk factor for deafness raises the possibility that there may be other variants in its coding sequence that exhibit a similar hearing deficit." (PMID 29590114, 2018).
autism spectrum disorder (2 papers, 2018 to 2021). A spectrum of developmental disorders that includes autism, and Asperger syndrome. "Two candidate single nucleotide polymorphisms, rs35671301 (p.Ser419Ala) and rs17155147 (p.Thr1267Met), in human PPIP5K2 were reported to be enriched in individuals with autism spectrum disorder." (PMID 29590114, 2018).
hearing loss (2 papers, 2018 to 2024). "Exome enrichment followed by massive parallel sequencing revealed a c.2510G>A transition variant in PPIP5K2 that segregated with DFNB100-associated hearing loss in two large apparently unrelated Pakistani families." (PMID 29590114, 2018). "We have shown that a pathogenic variant in PPIP5K2 is associated with hearing loss in humans." (PMID 29590114, 2018).
ovarian carcinoma (2 papers, 2022). A malignant neoplasm originating from the surface ovarian epithelium. "We showed that PPIP5K2 was associated with the progression of ovarian cancer." (PMID 35813475, 2022). "Taken together, the physical interaction of LncOVM and PPIP5K2 suppressed the ubiquitination and subsequent proteasomal degradation of PPIP5K2 in ovarian cancer cells." (PMID 35813475, 2022). "More importantly, the high level of PPIP5K2 expression was well corrected with poor prognosis of ovarian cancer patients accordingly, for instance, the overall survival that was revealed by Kaplan-Meier analysis on AOCS and TCGA databases." (PMID 35813475, 2022). "We further asked if any secretion proteins are impacted by PPIP5K2 and play crucial role in ovarian cancer progression." (PMID 35813475, 2022). "The extent and length of Golgi complex were reduced in ovarian cancer cells with depletion of LncOVM or PPIP5K2, which were with lower metastasis level compared with the wild type ovary cancer cells." (PMID 35813475, 2022). "To dissect its potential functions on the ovarian cancer progression, we knocked down PPIP5K2 to explore its effects on the metastatic ability of ovarian cancer cells." (PMID 35813475, 2022). "For instance, LncRNA OVM interacts with and stabilizes PPIP5K2 by reducing its ubiquitinated degradation, allowing ovarian cancer cells to secrete complement C5." (PMID 36471363, 2022). "LncOVM interacts with and stabilizes PPIP5K2 by suppressing ubiquitinated degradation to promote complement C5 secretion from ovarian cancer cells." (PMID 35813475, 2022).
adenoma (1 paper, 2022). A neoplasm arising from the epithelium. "Several of the genes encoding kinase presented isoforms, resulting from alternative splicing of mRNA: kinases PAK7 and STK26 in NR5A1-derived tumors, kinase PPIP5K2 in POU1F-derived adenomas and kinases like PPIP5K2 and kinases WEE1 and STK17 in the TBX19 tumors." (PMID 35260162, 2022).
age (1 paper, 2018). A temporal measurement of the time period elapsed since an identifiable point in the life cycle of an organism. "Future studies with mice in which the Ppip5k2 gene is targeted on a genetic background resistant to age-related HL, may also help in deciphering the roles of PP-IPs in development, maintenance and function of sensory cells in the inner ear." (PMID 29590114, 2018).
cervical cancer (1 paper, 2021). A primary or metastatic malignant neoplasm involving the cervix. "The remaining 10 genes (i.e., YJEFN3, SPATA5L1, C5orf55, PPM1A, IMMP1L, ZNF330, PPIP5K2, ESCO2, FICD, and ZNF225) are not directly reported to be related to the survival risk of cervical cancer in previous literature." (PMID 34149809, 2021).
colon cancer (1 paper, 2021). "In keeping with this interpretation, silencing of PPIP5K2 led to decreased cell proliferation in colon cancer cells." (PMID 33846320, 2021).
corneal opacities (1 paper, 2019). "The corneal opacities, abnormal cornea structure and surface irregularities observed in the Ppip5k2+/K^ and Ppip5k2K^/K^ mice have the potential to impair visual function by interfering with the amount of light reaching the retina." (PMID 31852976, 2019).
lung carcinoma (1 paper, 2024). "There have not yet been any studies that investigate the role of PPIP5K2 in lung cancer metastasis." (PMID 38339341, 2024). "Nevertheless, there are currently no reports on PPIP5K2 in lung cancer." (PMID 38339341, 2024).
Obesity (1 paper, 2023). Accumulation of substantial excess body fat. "While the eGenes, PAM, GIN1, and PPIP5K2, have not been studied in the context of obesity and metabolism, they have been studied for their function in other cell types." (PMID 37326626, 2023).
Parkinson disease (1 paper, 2024). A progressive degenerative disorder of the central nervous system characterized by loss of dopamine producing neurons in the substantia nigra and the presence of Lewy bodies in the substantia nigra and locus coeruleus. "We nominated candidate genes in each locus and identified novel pathways potentially involved in Parkinson’s disease, such as the inositol phosphate biosynthetic pathway (INPP5F, IP6K2, ITPKB and PPIP5K2)." (PMID 37804111, 2024).
viral infection (1 paper, 2020). "PPIP5K2 exon inclusion is also increased upon viral infection, producing increased levels of the canonical full-length isoform of the RNA." (PMID 33269701, 2020).
cancer (4 papers, 2021 to 2025). A tumor composed of atypical neoplastic, often pleomorphic cells that invade other tissues. "A previous study described how loss-of-function of PPIP5K2 alters energy metabolism in cancer cell lines." (PMID 41533938, 2025). "To further investigate the underline mechanism of cancer progression caused by LncOVM, we further explored whether and how LncOVM regulates PPIP5K2." (PMID 35813475, 2022). "Nevertheless, few relevant reports of PPIP5K2 in other cancer types, particularly NSCLC, have been found." (PMID 38339341, 2024). "Moreover, we found that the expression level of PPIP5K2 in NSCLC cancer tissues was much higher than its paired paracancerous tissues in the GEO database (GSE19804)." (PMID 38339341, 2024). "LncOVM formed a complex with protein PPIP5K2 and remodeled the structure of Golgi complex, leading to the enhanced complement C5 secretion and MDSC infiltration in TME, which promoted cancer metastasis." (PMID 35813475, 2022). "PPIP5K2, a bifunctional inositol kinase, has never been known its function in cancer, although it is reported to regulate various biological processes such as apoptosis, vesicle trafficking, cytoskeletal dynamics, and exocytosis 23-25." (PMID 35813475, 2022).
infection (3 papers, 2014 to 2019). The state of being infected such as from the introduction of a foreign agent such as serum, vaccine, antigenic substance or organism. "It is therefore significant that we also found silencing of IPPK, PPIP5K1 and PPIP5K2 dampened IFNβ transcription during infection of HEK293 cells by Sendai virus (SeV), a known stimulator of RIG-I." (PMID 24586175, 2014). "Detailed genetic and biochemical experiments demonstrated that the kinase activities of IPPK, PPIP5K1 and PPIP5K2 (which convert IP5 to1-IP7) were critical for both interferon induction, and the control of cellular infection by Sendai and influenza A viruses." (PMID 24586175, 2014). "Furthermore, we also found that HEK293 cells were more resistant to infection with influenza A virus upon over expression of either IPPK, PPIP5K1 or PPIP5K2." (PMID 24586175, 2014).
tumor (2 papers, 2022 to 2024). "Again, we observed a significant decrease of tumor volumes with obvious E-cadherin increase and vimentin decrease when PPIP5K2 was depleted." (PMID 35813475, 2022). "To confirm the pro-tumor role of PPIP5K2 collaborating with the LncOVM, we generated a PPIP5K2-overexpressing A2780s cell line." (PMID 35813475, 2022). "Knockdown of LncOVM or PPIP5K2 inhibits tumor progression in xenograft models." (PMID 35813475, 2022).
PPIP5K2 also shares sentences with these, for which no sentence is quoted: autosomal recessive deafness (1 paper); breast carcinoma (1); diabetes (1); glaucoma (1); Intellectual disability (1); neuroblastoma (1).